ARID1A (AT-rich interaction domain 1A)
Diseases named in the same sentence as ARID1A in open-access papers (continued):
Sharing a sentence is not in itself a finding about the gene and the disease.
clear cell carcinoma (continued). "We performed immunohistochemical staining for ARID1A in 78 ovarian endometriosis samples and 99 clear cell carcinoma samples." (PMID 32868822, 2020). "ARID1A immunohistochemical staining of frozen sections was similar to that of FFPE samples in two clear cell carcinomas and ovarian endometriosis case." (PMID 32868822, 2020). "Clear cell carcinoma frequently has both PIK3CA mutation (oncogene) and ARID1A mutation (tumor suppressor gene)." (PMID 30971221, 2019). "ARID1A and PIK3CA mutations were particularly important in the clear cell carcinoma subtype of EAOC." (PMID 29743986, 2018). "The results of the ATARI trial will provide the first indication of whether there is clinical activity of ATR inhibitors in clear cell carcinomas and other rare gynecological cancers according to ARID1A status." (PMID 34518240, 2021). "Nine clear cell carcinomas with ARID1A mutations and four clear cell carcinomas without ARID1A mutations were excluded from this analysis because of the low antigenicity or low quality of FFPE section samples." (PMID 32868822, 2020). "(A) The number of clear cell carcinomas with or without ARID1A protein expression and/or ARID1A mutations is shown." (PMID 32868822, 2020). "Notably, clear cell carcinomas were marked by high prevalence of PI3KCA and ARID1A mutations (67% and 50% for PIK3CA and ARID1A, respectively), compared to HGSC and other EOC types (P = 1.067 × 10−05 and P = 5.43 × 10−04)." (PMID 31771620, 2019). "The gene ARID1A, encoding BAF250a, a component of the SWI-SNF chromatin remodeling complex, was found to be mutated in 46% of clear cell carcinomas, 30% of endometrioid ovarian cancer and never mutated in serous ovarian cancer." (PMID 29389895, 2018). "Our case, in which increased AKT phosphorylation was induced by loss of ARID1A rather than by PIK3CA mutation, could have resulted in clear cell carcinoma if not treated." (PMID 41574315, 2026). "On the other hand, the expression of ARID1A was maintained in teratoma, PNET, non-specific adenocarcinoma, and various types of sarcomas, suggesting that these tumors had an origin different from that of clear cell carcinoma." (PMID 35327349, 2022).
lung cancer (48 papers, 2016 to 2025). A malignant neoplasm involving the lung. "ARID1A deficiency leads to resistance to chemotherapy and cetuximab in patients with lung cancer and CRC through multiple mechanisms." (PMID 40750787, 2025). "Consistently, ARID1A deficiency in melanoma and lung cancer increases cytosolic double-stranded DNA fragments, thereby activating the cGAS-STING pathway and potentiating type-I interferon signaling." (PMID 41438758, 2025). "In this regard, IACS‐010759 treatment induced cell death in lung cancer cells harboring mutations in SMARCA4 or ARID1A." (PMID 38214418, 2024). "Huang’s team utilized NOD-SCID-IL2RgammaC-null mice to establish a PDX model using tumor tissue from patients with AT-Rich Interaction Domain 1A (ARID1A)-mutated lung cancer." (PMID 39204153, 2024). "Consistent with the idea of harnessing metabolic vulnerability in ARID1A-deficient lung cancers, a recent study reveals that ARID1A loss promotes lung tumorigenesis through enhanced glycolysis." (PMID 36980292, 2023). "Strikingly, EGFR short variant (SV) was the top mutually exclusive alteration with ARID1A mutations in lung cancers." (PMID 36117191, 2022). "As one of the most frequently mutated genes, ARID1A is the most frequent target of mutations in ovarian, gastric and lung cancers, while the mutation of ARID1B is rarer than that of ARID1A." (PMID 34598711, 2021). "Based on analysis of the COSMIC database, NOTCH1 and ARID1A are reported to be associated with lung cancer." (PMID 34136379, 2021). "ARID1A is one of the most frequently mutated genes in many cancer types, particularly ovarian, breast, gastric, and lung cancers." (PMID 29890703, 2018). "In esophageal cancer and lung cancer, loss of ARID1A promotes invasive growth and metastasis." (PMID 38229120, 2024). "ARID1A mutations are detectable in about 6-7.5% of lung cancers." (PMID 36890819, 2023). "One case of poorly differentiated carcinoma of the lung had an ARID1A G836fs variant." (PMID 36125633, 2023). "ARID1A has previously been demonstrated to play an important function as a negative regulator, and its expression degree was linked to outcome in tumor patients with gastric, prostate, and lung cancers." (PMID 35028302, 2022). "Whether these mutations can be combined with NOTCH1, EGFR and ARID1A mutations as tumor markers in the diagnosis of early lung cancer merits further investigation." (PMID 34136379, 2021). "Since TM4SF1 has the ability to regulate Akt signaling and ARID1A loss leads to the activation of Akt signaling in lung cancer cells, we thus examined whether PLAU and TM4SF1 interaction is involved in the activation of Akt signaling in ARID1A-deficient lung cancer cells." (PMID 38229120, 2024). "Moreover, ARID1A-loss lung cancers had the worst survival in comparison to ARID1A-positive tumors." (PMID 36890819, 2023). "ARID1A has recently emerged as a novel tumor suppressor gene, as per the evidence supporting the positive association between reduced ARID1A expression and tumorigenicity of several cancers, such as ovarian, endometrial, cervical, breast, gastric, colorectal, and lung cancers." (PMID 34924820, 2021). "Inhibition of glycolysis is considered a therapeutic option for aggressive cancers, including lung cancer, and related genes can be used as potential targets for metabolic therapy against cancer cells, such as ARID1A and circ-ENO135–37." (PMID 38926418, 2024). "Hence, we checked whether targeting TM4SF1 can restrain ARID1A-mutated lung cancer growth." (PMID 38229120, 2024). "In vitro cell experiments showed that ARID1A knockout lung cancer cells were sensitive to ionizing radiation, cisplatin, and UV." (PMID 38427070, 2024). "The authors also experimentally verified the impact of ARID1A silencing in lung cancer cell lines, concluding that ARID1A has a tumor suppressive role in this tumor type." (PMID 36890819, 2023).
lung cancer (continued). "In the multivariable analysis, only lung cancer as well as the presence of ARID1A, KRAS, ALK, and MYC alterations and liver metastasis remained significant predictors of a poorer survival (all P < 0.50)." (PMID 29866143, 2018). "It was reported recently that EGFR expression is regulated by SMARCE1, SMARCA4, and ARID1A and that SMARCE1 deficiency confers TKI resistance in lung cancer." (PMID 27783942, 2016). "Of 5980 lung cancer patients with ARID1A and/or EGFR SVs, only 100 patients (1.7%) had both SVs." (PMID 36117191, 2022). "Notably, low expression of ARID1A is also shown to increase the immune response in lung cancer." (PMID 40429787, 2025). "In lung cancer, mutations in the chromatin remodeling complex SWI/SNF, such as the genes SWI/SNF Related, matrix associated actin dependent regulator of chromatin, subfamily A, member 4 (SMARCA4) and AT‐rich interactive domain‐containing protein 1A (ARID1A), sensitize cells to OXPHOS metabolism." (PMID 38214418, 2024). "Moreover, the results showed that ARID1A depletion could promote lung cancer cell proliferation and decrease sensitivity to the conventional chemotherapies, possibly by Akt-mediated cyclin D1 and Bcl-2 regulation." (PMID 36420141, 2022). "Alterations in ARID1A may be diverse and have been observed in many cancers, including lung cancer." (PMID 36420141, 2022). "ARID1A- and SMARCA4-mutant tumors were found to be more sensitive to the inhibition of OXPHOS when compared with wild-type controls in a lung cancer study." (PMID 37109525, 2023). "Similar enrichments of SGMs were seen in other core TSGs such as RB1, NF1, and ARID1A and emerging TSGs such as MGA, a transcription factor of the MYC network that suppresses growth and invasion in cellular and mouse models of lung cancer." (PMID 37922356, 2023). "Frequent ARID1A (the AT-rich interactive domain 1A [SWI-like] gene) depletion, detected in 20% of all lung cancers, induced chromatin remodeling and glycolysis, inhibiting cell death induced by the BRD4 inhibitor JQ1." (PMID 35831279, 2022). "ARID1A and CDKN2A are also on the top 20 cancer gene list in breast, colon, and lung cancers, and are found in an average of 7.4% and 4.2% cases, respectively, across all four common cancer types." (PMID 32570879, 2020). "Analysis indicated that CDKN2A, FAT1, MSH6, ARID1A, KEAP1, NF1, and SMAD4 mutation was more recurrent in patients with ERBB2 SNV/indels within the kinase domain compared with non-kinase domain in lung cancer." (PMID 35911441, 2022).
gynecological cancers (42 papers, 2012 to 2025). "In a comprehensive study involving 1432 patients with endometrium-associated gynecological cancers, loss of ARID1A expression predicted shorter PFS." (PMID 40862791, 2025). "The role of specific HDAC inhibitors, such as ACY1215, an HDAC6 inhibitor, further illustrates epidrugs’ therapeutic potential in ICI therapy for gynecological cancers with ARID1A mutations." (PMID 41029427, 2025). "ARID1A (AT-Rich Interaction Domain 1A) mutations are particularly prevalent in gynecological cancers and premalignant gynecological lesions, especially those of endometrioid origin." (PMID 39684461, 2024). "Inactivating mutations in the AT-rich interactive domain-containing protein 1A (ARID1A) are found more frequently in gynecological cancers, and in 14 gynecological cancer cell lines, loss of ARID1A caused increased levels of ROS." (PMID 38139406, 2023). "ARID1A mutations are particularly prevalent in gynecologic cancers (found in 10–60% of ovarian and endometrioid carcinoma cases) and pre-malignant gynecological lesions, especially of endometrioid origin." (PMID 36430148, 2022). "Although ARID1A expression loss has been described chiefly in gynecological cancers, it is reported among other tumor types, such as from gastrointestinal tract tumors." (PMID 32334542, 2020). "Given the heterogeneity of gynecologic cancers, a consistent relationship between the presence of an ARID1A mutation and prognosis has been elusive." (PMID 29093822, 2017). "As the molecular characterization of solid malignancies expanded, it became evident that ARID1A mutations were most pronounced in gynecologic cancers." (PMID 29093822, 2017). "Using gynecologic cancer cells, we validated that ARID1A deficiency led to increased sensitivity to treatment with elesclomol." (PMID 27486766, 2016). "Inactivating mutations in ARID1A are found in a broad spectrum of cancer types, with the highest frequency in gynecologic cancers." (PMID 27486766, 2016). "In the present study, we demonstrate for the first time that loss of ARID1A leads to accumulation of ROS in gynecologic cancer cells." (PMID 27486766, 2016). "Mutations in the ARID1A gene are a frequent event occurring in a wide variety of gynecological and non-gynecological cancers." (PMID 24979463, 2014). "In gynecologic cancers, loss of ARID1A is also regarded as an independent prognostic biomarker." (PMID 36123603, 2022). "ARID1A deficiency is observed in gynecological cancers such as ovarian cancer." (PMID 34885229, 2021). "Collectively, ARID1A loss reflected biological aggressiveness of gynecological cancers." (PMID 34257552, 2021). "The potential therapeutic role of EZH2 inhibition in ARID1A mutated gynecologic cancers may represent a novel and exciting treatment paradigm in a subset of patients with limited treatment options." (PMID 29093822, 2017). "Loss of ARID1A expression is frequent in a variety of cancers, especially in gynecologic cancers." (PMID 27323812, 2016). "In summary, we demonstrate for the first time that loss of ARID1A leads to accumulation of ROS and suggest that elesclomol may be used to target ARID1A-mutant gynecologic cancer cells." (PMID 27486766, 2016).
gynecological cancers (continued). "The existing studies focus on mutations in ARID1A, particularly in gynecologic cancers." (PMID 22808142, 2012). "Cancers with double alterations in ARID1A (ARID1A2+) were all gynecological cancers (83% endometrioid endometrial cancers)." (PMID 37711591, 2023). "Another interesting result in the present study was that the expression of ARID1A, a key subunit of the SWI/SNF complex and a common tumor suppressor gene frequently mutated in gynecologic cancers, positively correlated with the expression of PPARα." (PMID 37305395, 2023). "This analysis provides clinical and molecular details about the phenotypes of ARID1A+ cancers, in particular the subgroup of gynecologic cancers." (PMID 37711591, 2023). "Further investigation is highly needed to determine ARID1A’s potential as a gynecologic cancer biomarker." (PMID 36430148, 2022). "ATARI (ENGOT/GYN1/NCRI) is a multicenter, international, proof-of-concept, phase II, parallel cohort trial assessing ceralasertib activity as a single agent and in combination with olaparib in ARID1A stratified gynecological cancers." (PMID 34518240, 2021). "ARID1A is identified as a tumor suppressor gene in various cancers, especially gynecologic cancers, and an inverse correlation between ARID1A expression and tumor stage has been reported." (PMID 32961530, 2020). "Inactivating mutations of ARID1A, a subunit of the SWI/SNF chromatin remodeling complex, have been commonly reported in multiple human cancers, and especially in gynecological cancers." (PMID 31481116, 2019). "Our study suggests a novel therapeutic strategy for ARID1A-mutant gynecologic cancer cells by inducing oxidative stress." (PMID 27486766, 2016). "In a panel of 14 gynecologic cancer cell lines, treatment with elesclomol inhibited growth and induced apoptosis more potently in ARID1A-mutant cells." (PMID 27486766, 2016). "Mutations in the gene encoding the AT-rich interacting domain containing protein 1A (ARID1A) are frequently observed in a wide variety of gynecological and non-gynecological cancers." (PMID 24979463, 2014). "The ongoing phase 2 study ATARI is investigating the impact of olaparib (PARPi) monotherapy and in combination with an ATR inhibitor drug (AZD6738) in gynecological cancers and compares tumors with and without ARID1A loss (NCT04065269)." (PMID 38184614, 2024). "Taken together, our findings suggest that ARID1A protects cells against oxidative stress and ROS-inducing agents may be used to target ARID1A-mutant gynecologic cancer cells." (PMID 27486766, 2016). "ARID1A (BAF250a), which promotes the formation of SWI/SNF chromatin remodeling complexes containing BRG1 or BRM, has emerged as a candidate tumor suppressor gene based on its frequent mutations in gynecological cancers." (PMID 22481926, 2012). "The ATARI trial (ENGOT/GYN1/NCRI) is a phase II randomized trial comparing response rates between ceralasertib alone and in combination with olaparib in patients with gynecologic cancers, including recurrent clear cell carcinoma, with or without a confirmed ARID1A deficiency." (PMID 34885229, 2021).
gynecological cancers (continued). "A metanalysis on the prognostic significance of ARID1A in endometrium-related gynecological cancers showed that negative ARID1A expression predicted shorter progression free survival." (PMID 37228503, 2023). "ERBB2, PIK3CA, ARID1A, and KRAS would be key molecular targets in gynecological cancers." (PMID 38201563, 2023). "In multivariable meta-regression analyses, significant moderators emerged only for all-cause mortality, including differences in percentage of low-grade cancers between ARID1A− vs. ARID1A+ and studies about gastrointestinal and gynecological cancers compared to urological cancers." (PMID 26384299, 2015).